ACSL4 (acyl-CoA synthetase long chain family member 4)
Description:
Catalyzes the conversion of long-chain fatty acids to their active form acyl-CoA for both synthesis of cellular lipids, and degradation via beta-oxidation. Preferentially activates arachidonate and eicosapentaenoate as substrates. Preferentially activates 8,9-EET > 14,15-EET > 5,6-EET > 11,12-EET. Modulates glucose-stimulated insulin secretion by regulating the levels of unesterified EETs (By similarity). Modulates prostaglandin E2 secretion. Acts as an activator of ferroptosis by activating polyunsaturated fatty acids, especially arachidonate and adrenate, to their active form, generating the primary lipid-peroxidation substrates that contribute to ferroptosis.
Synonyms: ACS4; FACL4; LACS4; MRX63; MRX68; XLID63
Tractability: Antibody: UniProt places it where antibodies can reach, with high confidence; its Gene Ontology location is reachable by antibodies, with high confidence; UniProt predicts a signal peptide or a membrane-spanning region. PROTAC: ubiquitination databases record sites on it; its protein half-life has been measured.
Target class: Enzyme; Ligase
Gene: Protein-coding gene on chromosome X (109,624,244 to 109,733,403, reverse strand). Ensembl gene ENSG00000068366.
Subcellular location: Mitochondrion outer membrane; Endoplasmic reticulum membrane; Cell membrane
Subcellular location (Human Protein Atlas): Golgi apparatus; Mitochondria
Pathways (Reactome):
Metabolism: Intracellular metabolism of fatty acids regulates insulin secretion; Synthesis of very long-chain fatty acyl-CoAs
Gene Ontology:
Molecular function: arachidonate-CoA ligase activity; long-chain fatty acid-CoA ligase activity; very long-chain fatty acid-CoA ligase activity; palmitoyl-CoA ligase activity
Biological process: lipid metabolic process; long-chain fatty acid metabolic process; positive regulation of ferroptosis; fatty acid metabolic process; long-chain fatty-acyl-CoA biosynthetic process; long-chain fatty-acyl-CoA metabolic process; neuron differentiation; positive regulation of insulin secretion; fatty acid biosynthetic process
Cellular component: cytoplasm; endoplasmic reticulum membrane; extracellular exosome; lipid droplet; membrane; mitochondria-associated endoplasmic reticulum membrane contact site; mitochondrial outer membrane; mitochondrion; plasma membrane
Gene-disease validity (ClinGen):
ClinGen rates the evidence that ACSL4 causes each of these diseases.
non-syndromic X-linked intellectual disability (X-linked): Definitive.
Homologues: Orthologues: macaque ACSL4 (99% identical), chimpanzee ACSL4 (99% identical), rabbit ACSL4 (98% identical), dog ACSL4 (97% identical), rat Acsl4 (97% identical), pig ACSL4 (97% identical), mouse Acsl4 (97% identical), guinea pig ACSL4 (94% identical), tropical clawed frog acsl4 (82% identical), zebrafish acsl4a (76% identical), zebrafish acsl4b (68% identical), Caenorhabditis elegans acs-15 (26% identical), and 23 more. Paralogues in human: ACSL3 (67% identical), ACSL6 (31% identical), ACSL1 (30% identical), ACSL5 (30% identical), ACSBG2 (22% identical), ACSBG1 (20% identical), SLC27A4 (18% identical), SLC27A5 (17% identical), SLC27A3 (17% identical), SLC27A1 (16% identical), SLC27A2 (16% identical), SLC27A6 (16% identical).
Diseases named in the same sentence as ACSL4 in open-access papers:
ACSL4 is named in the same sentence as 252 diseases in open-access papers, as found by Europe PMC text mining. Sharing a sentence is not in itself a finding about the gene and the disease. The quoted sentences say what the papers report.
breast cancer (102 papers, 2010 to 2026). A primary or metastatic malignant neoplasm involving the breast. "It has been reported that higher ACSL4 expression is associated with better survival in breast cancer patients receiving paclitaxel-cisplatin-based neoadjuvant chemotherapy." (PMID 40027180, 2025). "It is reported that the glutamine-dependent breast cancer (BC) subgroup is sensitive to ferroptosis, and this sensitivity is associated with ACSL4 expression." (PMID 41502519, 2025). "ACSL4 has been implicated in ferroptosis, as proven in a breast cancer cell line study where cell lines showing ACSL4 are responsive to ferroptosis." (PMID 38660623, 2024). "With regards to breast cancer, studies have reported that ACSL4 overexpression is associated with an aggressive breast cancer phenotype and promotes resistance to hormone therapy." (PMID 38548749, 2024). "Survival analysis revealed that breast cancer patients with high expression of both ACSL4 and ZEB2 are associated with worse overall survival than those patients with low expression." (PMID 38078907, 2023). "Data also suggest that ACSL4 plays a role in conferring susceptibility to breast cancer tumorigenesis associated with the expression of the PADI2 gene." (PMID 37306503, 2023). "The function of ACSL4 in breast cancer has been implicated in hormone therapy resistance involving the regulation of energy-dependent transporter expression." (PMID 38078907, 2023). "In oestradiol-treated breast cancer cells, ACSL4 was implicated in increasing the cellular uptake of polyunsaturated FAs and enhancing cancerous growth." (PMID 35448537, 2022). "ACSL4 has also been implicated in drug resistance in breast cancer cell lines through the regulation of ATP-binding cassette (ABC) transporter expression." (PMID 36497375, 2022). "The findings of this work showed that PPIII causes ferroptosis via ACSL4 in MDA-MB-231 breast cancer cells, whereas xCT inhibition made breast cancer cells more sensitive to PPIII." (PMID 36355532, 2022). "On the other hand, some studies showed that ACSL4 is associated with the development and progression of multiple cancers, including breast cancer, colorectal cancer, and hepatocellular carcinoma." (PMID 34053456, 2021). "Basal-like breast cancer cell lines are susceptible to ferroptosis due to the expression of acyl-CoA synthetase long-chain family member 4 (ACSL4) which enriches cellular membranes with long polyunsaturated fatty acids (PUFAs)." (PMID 33672555, 2021). "Regarding functional aspects, our group and others have established ACSL4 involvement in the mechanism underlying increased breast cancer cell proliferation, invasion and migration, in vitro and in vivo." (PMID 31311992, 2019). "High ACSL4 expression is inversely associated with estrogen receptor expression and high ACSL4 expression is a biomarker for an aggressive breast cancer phenotype." (PMID 30388870, 2018). "Results of experiments in breast cancer cell lines suggest that simultaneous expression of ACSL4 and a receptor is associated with hormone resistance." (PMID 24155918, 2013). "ACSL4 status is clearly associated with claudin-low, and to a lesser extent, basal-like breast cancer." (PMID 24155918, 2013). "Our results, in terms of its overexpression and inhibition, demonstrate that ACSL4 plays a causal role in the control of breast cancer aggressiveness." (PMID 21085606, 2010). "ACSL4 expression is associated with aggressive phenotype in breast cancer cells." (PMID 40002245, 2025). "In addition, we also provide evidence that overexpression of ZEB2 or ACSL4 is associated with worse prognosis in advanced breast cancer." (PMID 38078907, 2023). "ACSL4 has been shown to be associated with the aggressive phenotype of breast cancer." (PMID 27765921, 2017). "The ability of ACSL4 to cause a decrease in X inactive specific transcript (XIST) in both MCF-7 models is of interest in light of the data implicating a possible role for this RNA moiety in the genesis of breast cancer." (PMID 24155918, 2013).
breast cancer (continued). "Finally, ACSL4 has been demonstrated to be one of three downstream targets of FOXM1-induced migration in MDA-MB-231 cells as well as a mediator of the tumorigenic role of PADI2 in conferring susceptibility to breast cancer." (PMID 28412757, 2017). "For instance, in breast cancer, ACSL4 modulates ferroptosis to influence disease progression and treatment outcomes." (PMID 40395328, 2025). "In breast cancer, PKCβII activates ACSL4 through phosphorylation to increase ferroptosis-related lipid peroxidation." (PMID 40050614, 2025). "Existing studies have demonstrated that ACSL4 represents a promising therapeutic target for breast cancer, hepatic disorders, and renal diseases." (PMID 40901058, 2025). "The genetic signaling pathway initiated by BQ overexpression, which disrupts the NCOR2–PPARγ interaction to de-repress ACSL4, positions BQ as a transcriptional hub in breast cancer." (PMID 40507798, 2025). "ACSL3 and ACSL4 have been shown to enhance the metastatic potential of colorectal carcinoma and breast cancer through increased FAO." (PMID 40507798, 2025). "In the present study, we revealed that S-palmitoylation of MTDH negatively regulates its interaction with ACSL4, thereby modulating the ferroptosis sensitivity in breast cancer cells." (PMID 41318030, 2025). "PDP2 expression is associated with the prognosis of breast cancer, and PDP2 dephosphorylation inhibits ACSL4 activity, inducing ferroptosis in tumor cells." (PMID 40746885, 2025). "RNA sequencing of BQ-overexpressing breast cancer cells revealed significant enrichment of fatty acid metabolism pathways (hsa01212 and hsa00061; p < 0.05), with ACSL4 identified as a key target." (PMID 40507798, 2025). "The interplay between ACSL4, FASN, and SCD underscores a coordinated lipid metabolism axis in BQ-driven breast cancer, with ACSL4 as the key effector of energy production, potentially supporting metastatic potential by providing energy for EMT and invasion." (PMID 40507798, 2025). "The non-S-palmitoylation form of MTDH-CS enhanced the interaction between MTDH and the ferroptosis enhancer of Acyl-CoA synthetase long-chain family member 4 (ACSL4), thereby reducing ferroptosis sensitivity in breast cancer cells." (PMID 41318030, 2025). "In breast cancer, ACSL4 expression is strongly correlated with ferroptosis sensitivity; in specific basal-like cell lines, ACSL4 promotes PUFA uptake and enhances susceptibility." (PMID 41008615, 2025). "Transcription factor ZEB2 activates ACSL4 expression by directly binding to the ACSL4 promoter, thereby promoting cellular lipid storage and fatty acid oxidation to drive breast cancer metastasis." (PMID 40050614, 2025). "This study is the first to report that MAP4K4 plays a crucial role in mediating the radioresistance of breast cancer by acting upstream of ACSL4 to enhance DNA damage response and inhibit apoptosis." (PMID 38548749, 2024). "This study provides evidence that targeting MAP4K4 can overcome radioresistance of breast cancer by downregulating ACSL4, which suppresses DNA damage response and ultimately induces apoptosis." (PMID 38548749, 2024). "Elevated ACSL4 levels, accompanied by increased mitochondrial phospholipid biosynthesis and fatty acid oxidation, promote anti-apoptosis in chemoresistant breast cancer, and ACSL4 silencing suppresses tumor growth and induces apoptosis." (PMID 38539505, 2024). "As reported, a high ACSL4/low GPX4 profile holds significant practical value in predicting pathological complete response to neoadjuvant chemotherapy in patients with breast cancer." (PMID 39867656, 2024). "Overall, our results indicate that there is an interaction between MAP4K4 and ACSL4 that mediates radioresistance in breast cancer cells, with MAP4K4 acting as an upstream effector of ACSL4." (PMID 38548749, 2024). "Preclinical studies have revealed that ACSL4 can be activated in drug-resistant breast cancer cells." (PMID 39834807, 2024).
breast cancer (continued). "As a driver of ferroptosis, ACSL4 can also be used as a reference indicator of ferroptosis sensitivity, and breast cancer cell lines with preferential expression of ACSL4 have demonstrated increased susceptibility to ferroptosis." (PMID 37548939, 2024). "ACSL4 was highly expressed in basal-like breast cancer cell lines, enriching their membranes with AA and predisposing cells to ferroptosis." (PMID 39375460, 2024). "Previously, a positive correlation was shown between the expression of acyl-CoA synthetase long-chain family member 4 (ACSL4) and ferroptosis sensitivity in a subset of breast cancer cell lines." (PMID 39375460, 2024). "Collectively, the findings from this study highlight the ability of polyphyllin III to induce ferroptosis in MDA‐MB‐231 breast cancer cells through ACSL4, underscoring its potential as an effective anticancer agent." (PMID 38140764, 2024). "In this study, we identified MAP4K4 as an upstream effector of ACSL4 in radioresistant breast cancer cells." (PMID 38548749, 2024). "Studies conducted in breast cancer cells have demonstrated that silencing ACSL4 can significantly reduce the production of polyunsaturated fatty acids and suppress ferroptosis." (PMID 39524900, 2024). "ACSL4 sensitizes breast cancer cells to ferroptosis, whereas pharmacological ACSL4 inhibition prevents ferroptosis." (PMID 39434776, 2024). "ACSL4 is upregulated in several cancers including hepatocellular carcinoma, colorectal cancer, prostate cancer, and breast cancer." (PMID 38370339, 2024). "In our previous study, we demonstrated that acyl-CoA synthetase-4 (ACSL4) contributes to radioresistance in breast cancer cells by enhancing DNA damage response and inhibiting apoptosis." (PMID 38548749, 2024). "The high ACSL4/low GPX4 profile holds significant practical value in predicting pathological complete response to neoadjuvant chemotherapy in breast cancer.A strategy to enhance chemosensitivity through the induction of ferroptosis has been identified." (PMID 39867656, 2024). "To further validate our in vitro findings, we examined the effect of ACSL4 on lung metastasis of breast cancer cells in an animal model." (PMID 38078907, 2023). "A study comparing protein expression in luminal B versus basal-like breast cancer samples clearly indicates that ACSL4 protein is more highly expressed in the basal-like subset." (PMID 37306503, 2023). "(C) The correlation between ACSL4 and ERɑ mRNA expression in the TCGA cohort consisting of 1222 breast cancer patient samples." (PMID 38078907, 2023). "(I) The correlation between ACSL4 and ERɑ protein expression in the IHC cohort consisting of 45 breast cancer patient samples." (PMID 38078907, 2023). "The future study should expand the clinical samples and cases to provide more clinical evidence for the crucial role of ACSL4 in breast cancer metastasis." (PMID 38078907, 2023). "There are limited proteomic data with respect to breast cancer subtypes; however, these data also support the conclusion that ACSL4 is differentially overexpressed in basal-like breast cancers." (PMID 37306503, 2023). "In fact, ACSL4 expression has also been suggested to be positively correlated with immune infiltration in breast cancer." (PMID 37306503, 2023). "With respect to breast cancer, expression of ACSL4 protein would strongly suggest insensitivity to receptor-targeted treatment while indicating potential sensitivity to induced ferroptosis." (PMID 37306503, 2023). "ACSL4 promotes drug resistance in breast cancer cell lines by regulating the expression of energy‐dependent transporters." (PMID 37746665, 2023). "While the use of receptor biomarkers in the diagnosis and treatment of breast cancer has proved extraordinarily useful, perhaps it is time to consider adding routine measurement of ACSL4 protein as a predictive indicator in the management of breast cancer." (PMID 37306503, 2023).
breast cancer (continued). "Several studies suggest that ACSL4 can be used as a biomarker and mediator for the invasive breast cancer phenotype." (PMID 37746665, 2023). "ACSL4 is upregulated in many cancers, including liver cancer, prostate cancer, breast cancer, and colon cancer." (PMID 36728187, 2023). "In gastric cancer, glioma, lung adenocarcinoma and breast cancer, ACSL4 is regarded as a tumor-suppressive factor." (PMID 37193981, 2023). "Among them, Robustaflavone 7,5′′-dimethyl ether (RF-A) exhibite the ability to induce ferroptosis in breast cancer cells by downregulating ACSL4 protein expression." (PMID 37920209, 2023). "It is worth noting that ACSL4 is upregulated in therapy-resistant prostate and breast cancer, in which RB1 inactivation most commonly occurs." (PMID 36928314, 2023). "Based on data derived from 71 breast cancer cell lines, positive ACSL4 expression predicted QNBC status with a sensitivity of 78% and a specificity of 86%." (PMID 37306503, 2023). "As observed for breast cancer, the presence of both ACSL4 and androgen receptor in prostate cancer cells predicts resistance to androgen deprivation therapies." (PMID 37306503, 2023). "Conversely, data support a role for FOXM1 in mediating ACSL4-induced radioresistance in breast cancer cells." (PMID 37306503, 2023). "Elevated ACSL4 levels can be used as an effective marker for predicting cancer progression in patients with advanced breast cancer." (PMID 38078907, 2023). "Data presented above support a role for ACSL4 activity in inducing a more aggressive form of breast cancer." (PMID 37306503, 2023). "Unlike GPX4, which has been demonstrated to be downregulated in breast cancer cells, ACSL4 has been verified to be substantially expressed in breast cancer tissues." (PMID 37488128, 2023). "As ACSL4 promotes intracellular LDs accumulation in breast cancer cells, we investigated the effect of ACSL4 on the lipid composition of breast cancer cells." (PMID 38078907, 2023). "The transcription factor, FOXM1, has been demonstrated to effect breast cancer cell migration; and functional assays in MDA-MB-231 mesenchymal breast cancer cells implicate ACSL4 as possible mediator of the FOXM1 effect." (PMID 37306503, 2023). "In breast cancer, acyl-CoA synthetase long-chain family member 4 (ACSL4) catalyzed the esterification of arachidonic acid and adrenic acid and promoted the formation of lipid peroxides." (PMID 38259464, 2023). "Taken together, these data suggest that ACSL4 promotes the lung metastasis of breast cancer cells in vivo." (PMID 38078907, 2023). "As expected, overexpression of ACSL4 significantly restored the invasive and metastatic capacities of ZEB2 knockdown cells by 35.1% and 32.4%, respectively, indicating that ACSL4 is essential for ZEB2-mediated breast cancer invasion and migration." (PMID 38078907, 2023). "More importantly, AA was essential to enhance the ferroptosis sensitivity induced by ACSL4 in breast cancer." (PMID 36243728, 2022). "Nevertheless, there were also evidences that ACSL4 overexpression increased the aggressiveness of breast cancer." (PMID 35910359, 2022). "ACSL4 is closely related to ferroptosis, and its abnormal expression can lead to hepatocellular carcinoma, breast cancer and other diseases." (PMID 35954183, 2022). "Recently, clinical studies demonstrated that higher ACSL4 expression was related with enhanced sensitivity to neoadjuvant chemotherapy in breast cancer, leading to a better overall survival." (PMID 35910359, 2022). "Alternatively, forced expression of ACSL4 is observed in a variety of tumors, including hepatocellar carcinoma, colon adenocarcinoma, and aggressive breast cancer." (PMID 36503536, 2022).